SOX2 (SRY-box transcription factor 2)
Diseases named in the same sentence as SOX2 in open-access papers (continued):
Sharing a sentence is not in itself a finding about the gene and the disease.
diabetes (7 papers, 2010 to 2023). "Since dedifferentiation is a vital program of SCs in wound healing, we observed Sox2+ cells in the wound area in C57 control mice (C57) and mice with streptozotocin (STZ)-induced diabetes (C57-STZ)." (PMID 35910794, 2022). "Likewise, the reduced SOX11 expression in D13.1βHet SOX2+ progenitors and early MPCs found in our HNF1B-deficient pancreatic cell differentiation model could at least partially explain the organ hypoplasia found in patients with HNF1B-associated diabetes." (PMID 34450036, 2021). "Immunocytochemistry further validated robust expression of diverse pluripotency markers, including SSEA-4, TRA-1-60, TRA-1-81, OCT4, SOX2, KLF4 and NANOG in HK-derived iPS clones regardless of patient age and status of diabetes." (PMID 22308265, 2012).
germ cell tumor (7 papers, 2009 to 2023). A benign or malignant, gonadal or extragonadal neoplasm that originates from germ cells. "TCam-2 has elevated H3K4me3 and H3K27ac for SOX17 and low H3K4me3 and H3K27ac for SOX2 whereas NCCIT, an EC cell line derived from a mediastinal germ cell tumor, has elevated H3K4me3 and H3K27ac for SOX2 and low H3K4me2 and H3K27ac for SOX17." (PMID 36835562, 2023). "Proteins were closely linked to proteins such as SOX-2, SOX-17, NANOG, or OCT3/4, which all have been described to play crucial roles in pluripotency and differentiation of germ cells and germ cell tumors." (PMID 31565104, 2019).
invasive carcinoma (7 papers, 2011 to 2024). A carcinoma that is not confined to the epithelium, and has spread to the surrounding stroma. "Tumors originating from AT2 cells continuously showed an NKX2-1+/SOX2– pattern from early hyperplastic lesions to invasive carcinoma (left)." (PMID 38093367, 2023). "Next, we studied the expression of MTA3/SOX2 in normal tongue tissue samples, hyperplasia, carcinoma in situ, early invasive carcinoma and invasive carcinoma by immunohistochemistry." (PMID 31552166, 2019). "The current hypothesis suggests that SOX2 is involved in various stages of invasive carcinoma development from normal epithelium, driving the expression of squamous histology markers such as P63." (PMID 38628662, 2024).
metastatic melanoma (7 papers, 2015 to 2025). A melanoma that has spread from its primary site to another anatomic site. "Among them, CD8A, SOX2, TYR, CXCL10 and ICAM1 had the most interaction with other proteins associated with metastatic melanoma." (PMID 39820173, 2025). "Together, these results suggest that Usp9x is overexpressed in metastatic melanoma and might contribute to stabilization of SOX2." (PMID 33613844, 2021). "This may suggest the dispensability of SOX2 following metastasis, as observed in metastatic malignant melanoma." (PMID 32850316, 2020). "If SOX2 is dispensable following metastasis in mHNcSCC as in metastatic malignant melanoma, a correlation between low SOX2 expression levels and a more aggressive cancer may be expected." (PMID 32850316, 2020). "Using the same iPSC markers, we have also shown the presence of two CSC subpopulations within head and neck metastatic malignant melanoma (HNmMM): an OCT4+/SOX2+/KLF4+/c-MYC+ CSC subpopulation within the TNs, and another in the PTS with NANOG present only in two of the 20 cases studied." (PMID 32850316, 2020). "Primary metastatic melanoma samples demonstrated moderately elevated Usp9x and SOX2 protein expression compared to tumors without metastatic potential." (PMID 33613844, 2021).
Obesity (7 papers, 2020 to 2025). Accumulation of substantial excess body fat. "Interestingly, SOX2 expression in NeuN-expressing cells is lost with aging and with obesity induced diets; SOX2′s role in this cell type deserves investigation." (PMID 35626641, 2022). "High AMD1 level could promote SRY‐box transcription factor 2 (SOX2), Kruppel like factor 4 (KLF4), and NANOG expression of HCC cells through obesity–associated protein (FTO)‐mediated mRNA demethylation." (PMID 33783988, 2021). "We suggest that the absence of effects on SOX2 expression indicates the absence of SOX2 participation in the regulation of adipo-osteogenic balance during obesity." (PMID 35629356, 2022).
skin squamous cell carcinoma (7 papers, 2017 to 2023). A carcinoma arising from the squamous cells of the epidermis. "With regard to CSCs, Sox2-positive skin squamous cell carcinoma cells express high levels of CSC markers CD133 and CD34, and exhibit enhanced tumorigenicity." (PMID 30518951, 2018). "Furthermore, Sox2 expression marks the tumor-initiating cell population of skin squamous cell carcinomas once Sox2 expression is induced during tumorigenesis." (PMID 31041783, 2019). "In a transplantation study of skin squamous cell carcinoma (SCC) in mice, they showed that SOX2 marked skin SCC tumor-propagating cells." (PMID 35055392, 2022).
cataract (6 papers, 2010 to 2024). Partial or complete opacity of the crystalline lens of one or both eyes that decreases visual acuity and eventually results in blindness. "Since expression during lens development represents an important site of SOX2 protein activity, some mutations may lead to phenotypes associated with specific loss of SOX2-related activity in the lens, such as cataracts and anterior segment defects." (PMID 35148715, 2022). "Since expression during lens development represents an important site of SOX2 activity, it is possible that some mutations may lead to phenotypes associated with specific loss of SOX2-related activity in the lens, such as cataracts and anterior segment defects." (PMID 20454695, 2010). "We first efficiently reprogrammed HLECs from age-related cataract patients to iPSCs with OCT-4, SOX-2, and KLF-4." (PMID 22403680, 2012).
Cognitive impairment (6 papers, 2018 to 2024). Abnormal cognition is characterized by deficits in thinking, reasoning, or remembering. "As expected, the number of SOX2+ neurons significantly decreased, indicating that the cognitive impairment caused by manipulating PDGF-BB secretion may be associated with neural progenitor cell loss." (PMID 38685040, 2024). "The SOX2 transcription factor is a key regulator of nervous system development, and its mutation in humans leads to a rare disease characterized by severe eye defects, cognitive defects, hearing defects, abnormalities of the CNS and motor control problems." (PMID 37108798, 2023). "Meanwhile, the number of SOX2+ neural progenitor cells was also significantly decreased in HFD-challenged mice, consistent with greater cognitive impairment in HFD-challenged mice." (PMID 38685040, 2024). "Previous studies have reported that cisplatin (a chemotherapeutic drug) can decrease the number of SOX2 positive cells in the SGZ of the dentate gyrus and induce cognitive deficits in the rat brain." (PMID 30096914, 2018).
cyst (6 papers, 2017 to 2024). A sac-like closed membranous structure that may be empty or contain fluid or amorphous material. "Intense staining for Sox2 was observed in the area where the inner cell cluster attached to the small cyst wall on the scleral side." (PMID 38892233, 2024). "We found that the SOX2-expressing cyst-like cells were unable to produce amylase in a manner similar to acinar cells, but large amounts of amylase were concentrated in the center of these structures." (PMID 35618699, 2022). "Co-staining of OCT4 with other pluripotency markers—NANOG and SOX2—confirms that the columnar side of the asymmetric cyst is composed of undifferentiated, epiblast-like cells, resembling the embryonic disc at one pole of the human amniotic sac." (PMID 28785084, 2017). "Strikingly, we found that SOX2 and GFP are specifically expressed in these cyst-like structures, despite being first activated in acinar cells." (PMID 35618699, 2022). "SOX-2 was absent in normal adult epithelium whereas positive SOX-2 staining was observed in CPAM lung tissue sections, localised to cyst-lining epithelial cells." (PMID 32732323, 2020). "In this case, we found a greater expression of SOX2 in OKC than AB, with noticeable staining in all cell layers of the cyst lining." (PMID 31967981, 2020). "This study shows that the embryonic airway epithelial cell markers SOX-2 and TTF-1 are retained in the cyst-lining epithelial cells of CPAM human lung tissue." (PMID 32732323, 2020).
dysplasia (6 papers, 2010 to 2023). A usually neoplastic transformation of the cell, associated with altered architectural tissue patterns. "Notably, SQCCs do not spontaneously arise in healthy epithelia, but do arise after years of smoking, and SOX2 amplification is commonly detected in dysplasia, in which it is associated with a higher rate of progression to SQCC." (PMID 27880766, 2016). "In the esophagus, SOX2 expression levels were gradually downregulated during normal esophageal squamous, BE metaplasia, dysplasia to EAC progression sequences." (PMID 36994101, 2023). "Cigarette smoke extract and nicotine induce activation of AKT, a downstream effector of PI3K signaling, in tracheobronchial basal cell cultures, and PI3K signaling is elevated in dysplasias when SOX2 amplification is common." (PMID 27880766, 2016). "We used primary human tracheobronchial basal cells to investigate how copy number gains in SOX2 and PIK3CA at 3q26-28, which co-occur in dysplasia and are observed in 94% of SQCCs, may promote progression." (PMID 27880766, 2016). "Five sections each from 40 histopathologically diagnosed cases of different grades of OED and 10 cases of normal oral mucosa without dysplasia were immunohistochemically stained with p16, ALDH1, CD44, SOX2, and OCT4, respectively." (PMID 34709167, 2021). "In this study we describe the expression of two transcription factors, CDX2 and SOX2, in a series of esophageal columnar metaplasia without IM (CLES) and with IM as well as in dysplasia and BA." (PMID 27766003, 2016).
Esophageal atresia (6 papers, 2008 to 2023). A developmental defect resulting in complete obliteration of the lumen of the esophagus such that the esophagus ends in a blind pouch rather than connecting to the stomach. "Sox2 mutations are associated with esophageal atresia in anophthalmia-esophageal-genital syndrome, and its down-regulation is associated with intestinal metaplasia in the stomach." (PMID 18190713, 2008). "Mouse models with reduced expression Sox2 or absence of Nkx2-1 resulted in separation defects, resembling the human congenital condition called tracheoesophageal fistula (TEF), where the airway is connected with the stomach and/or esophageal atresia (EA), a short and blunted esophagus." (PMID 36299482, 2022).
hypogonadotropic hypogonadism (6 papers, 2009 to 2023). Abnormal ovarian or testicular function due to insufficient hormonal stimulation from the hypothalamic-pituitary axis. "Pathogenic SRY-box transcription factor 2 (SOX2) variants typically cause severe ocular defects within a SOX2 disorder spectrum that includes hypogonadotropic hypogonadism." (PMID 36602867, 2023). "A connection to SOD was noted in a mouse model, and subsequent screening in a cohort of individuals with SOX2 variants identified pituitary hypoplasia and hypogonadotropic hypogonadism along with anomalies of the corpus callosum and medial temporal structures." (PMID 35885948, 2022). "In humans, heterozygous SOX2 loss-of-function mutations are associated with anophthalmia and hypogonadotrophic hypogonadism (reduced gonadal function of hypothalamic origin), while both SOX3 deletions and duplications are linked to mild hypopituitarism." (PMID 25587054, 2015). "Mutations in the Sox2 gene cause pituitary hypoplasia associated with hypogonadotrophic hypogonadism and eye, ear and encephalic abnormalities." (PMID 19283075, 2009). "Loss of Sox2 also significantly affects the number of GnRH neurons; therefore, the hypogonadotrophic hypogonadism displayed by human SOX2 patients is likely to be of hypothalamic origin." (PMID 25587054, 2015). "In addition to our data, humans with SOX2-related hypogonadotropic hypogonadism also showed intact pituitary responsiveness to a GnRH stimulation test (thus excluding a pituitary gonadotrope defect) and supporting a hypothalamic defect." (PMID 36602867, 2023). "Among the reported SOX2-related phenotypes, hypogonadotropic hypogonadism (HH) represents a commonly reported nonocular phenotype." (PMID 36602867, 2023).
idiopathic pulmonary fibrosis (6 papers, 2018 to 2025). Idiopathic pulmonary fibrosis (IPF) is a nonneoplastic pulmonary disease that is characterized by the formation of scar tissue within the lungs in the absence of any known cause. "SOX2 deficient dysplastic epithelium is found in lungs from both idiopathic pulmonary fibrosis and COVID-19 patients, suggesting conservation of this molecular barrier function across species." (PMID 38182591, 2024). "In idiopathic pulmonary fibrosis, loss of SOX2 expression correlates with increased WNT signaling activity in dysplastic keratinized epithelium." (PMID 38182591, 2024). "Loss of Sox2 promotes KRT17+KRT5– dysplastic epithelium after injury in the distal lung that is present in IPF lungs and patients with post-COVID-19 pulmonary fibrosis." (PMID 39927460, 2025). "In summary, our present data supports SOX2 regulation of COL1A1 promoter as a potential target in BP treatment of pulmonary fibrosis." (PMID 30287739, 2018). "As such, we postulate a possibility of the requirement of SOX2 in pulmonary fibrosis." (PMID 30287739, 2018). "Although our current study conducts a SOX2 knockout mice in animal models, the expression of SOX2 still reduces in BP-treated lung tissues, which supports our findings in the regulation of SOX2 and collagen, thus clarifying the therapeutic effects of BP in lung fibrosis." (PMID 30287739, 2018). "In conclusion, this study underscores the pivotal role of cellular senescence in the pathogenesis of idiopathic pulmonary fibrosis (IPF) and identifies four key CS-DEGs (CDKN2A, VEGFA, SOX2, and FOXO3) as potential biomarkers for diagnosis and targets for therapy." (PMID 40557159, 2025). "A study of MEG3 expression in idiopathic pulmonary fibrosis using scRNA-seq demonstrated that MEG3 regulates the differentiation of bronchial cells through diverse mechanisms, including through YAP1, NOTCH, and SOX2 signaling." (PMID 36231143, 2022). "All in all, these findings reveal a BP-induced non-canonical regulation of SOX2, and a potential candidate for the amelioration of pulmonary fibrosis." (PMID 30287739, 2018).
Infertility (6 papers, 2016 to 2025). "Next, to further examine the molecular mechanism underlying the infertility of Sox2-Cre+/−;Cul4bf/+ mice, we determined whether Cul4b deletion affected steroidogenesis in mouse ovaries." (PMID 39737063, 2025). "Global (Sox2-Cre) or germ cell-specific (Vasa-Cre) Cul4b knockout male mice are infertile with impaired spermatozoa motility and spermatogonial stemness." (PMID 39737063, 2025). "In this study, we generated Sox2-Cre+/−;Cul4bf/+ heterozygous female mice and found that these mice were infertile due to anovulation." (PMID 39737063, 2025). "Despite the fact that infertility observed in the current study may contribute, in part, by indirect effects from other tissues since the SOX2 gene is expressed in many tissues (e.g. brain and uterus) other than the ovary." (PMID 38504307, 2024). "PI4KB (involved in actin formation), SOX2 (essential for early embryonic development) and DPY19L2 (causes infertility by impairing head elongation, PLCζ signalling, acrosome formation and by causing globospermia) were downregulated in crossbred males, in microarray." (PMID 32693775, 2020). "We generated another line of Tg rats expressing human CD63-GFP under the Sox2 promoter, which expressed it in the kidney in addition to the brain; a large amount of urine output was observed, but no lethality or infertility was observed in either gender (unpublished)." (PMID 27539050, 2016).
Intellectual disability (6 papers, 2019 to 2023). "SOX2 mutations are associated with intellectual disabilities, seizures, and defective hippocampal development." (PMID 37830910, 2023). "In humans, SOX2 mutation leads to a spectrum of CNS defects, including vision and hippocampus impairments, intellectual disability, and motor control problems." (PMID 35626641, 2022). "The introduction of a functional Cr transporter in the CTD-rescue organoids leads to a reduction of GSK3β activation, a restoration of the SOX2 progenitor marker level, as well as of the highlighted proteins linked to intellectual disabilities such as PAK1 and MAP1B." (PMID 37830910, 2023). "Furthermore, postnatal hippocampal neurogenesis by NSC has been shown to contribute to learning and memory in mouse models, and its defects may contribute to the intellectual disability found in most SOX2-deficient patients." (PMID 35626641, 2022). "Human fibroblast cells from a patient with infantile-onset DM1 and a severe intellectual disability and from a control patient were transformed into iPSCs using the Sendai virus technique employing Yamanaka factors (OCT4, KLF4, MYC, and SOX2)." (PMID 35075265, 2022).
large cell carcinoma (6 papers, 2012 to 2023). A malignant epithelial neoplasm composed of large, atypical cells. "Here, we observed higher frequency of SOX2 copy number amplifications in squamous cell carcinoma tumors (59 %) than in adeno- (20 %) or large cell carcinoma (34 %)." (PMID 26780934, 2016). "Specifically, mice with LKB1 loss of function in conjunction with K-ras, PTEN or SOX2 developed metastatic lung tumors of varied pathologies, including ADC, SCC, and large-cell carcinoma." (PMID 37298489, 2023).
leukoplakia (6 papers, 2019 to 2025). A white patch or plaque on a mucous membrane that cannot be characterized clinically or pathologically as any other disease. "They detected SOX2 overexpression as an independent predictor of malignant transformation for oral leucoplakia, while SOX2 expression in OSCC was associated with early T and N stages and better survival." (PMID 35296132, 2022). "In our study, we found that the moderately or severely dysplastic leukoplakia expressed SOX2 to a similar extent to EOLP." (PMID 40568269, 2025). "The primary aim of this study is to assess the potentially malignant character of oral lichen planus (OLP) by identifying the CSC biomarkers OCT4 and SOX2 and comparing their pattern of expression to oral leukoplakia (OL) and normal oral mucosa (NOM)." (PMID 40568269, 2025). "The aim of this study was to detect the expression of embryonic-type CSC markers OCT3/4 and SOX2 in OSCCs and oral leukoplakias (OLs), the most common of OPMDs." (PMID 37859926, 2023). "The aim of this study was to investigate the immunohistochemical pattern of endothelial expression of SOX2 and CD147 in vessels beneath the epithelium of the most common OPMD, oral leukoplakia (OL), and OSCC." (PMID 38352102, 2024). "The mildly dysplastic or non-dysplastic leukoplakia group expressed OCT3-4 similarly to the reticular lichen planus group, while expressing SOX2 more than the reticular lichen planus group." (PMID 40568269, 2025). "Statistically significantly higher expression of SOX2 was observed in the erosive oral lichen planus (EOLP) group than in the reticular OLP (ROLP) group (p=0.05) and the mild and non-dysplastic leukoplakia group than in the reticular OLP group (p=0.024)." (PMID 40568269, 2025).